BRAF (B-Raf proto-oncogene, serine/threonine kinase)
Diseases named in the same sentence as BRAF in open-access papers (continued):
Sharing a sentence is not in itself a finding about the gene and the disease.
colon carcinoma (continued). "Sessile serrated tumors are a recently recognized class of colon cancers that present with BRAF mutations, as opposed to APC mutations, which are seen in the majority of colon cancer." (PMID 34138755, 2021). "In addition to FOLFOXIRI chemotherapy, BRAF and MEK inhibitors are being tested in clinical trials to treat BRAF mutated colon cancer." (PMID 34381786, 2021). "Given the central regulatory roles of NPM1 and c-Myc in these processes, their targeting could provide novel opportunities to counteract drug resistance in BRAF mutant colon cancer." (PMID 34201061, 2021). "In several clinical trials and observational cohorts, MSI-H and right-sided tumours were independent predictors of improved OS in stage II + III colon cancer, whereas BRAF-V600E mutations were not." (PMID 32823998, 2020). "Activation of EGFR results in unresponsiveness of colon cancer to BRAF(V600E) inhibition." (PMID 31896739, 2020). "On the other hand, BEV combination therapy is recommended for RAS or BRAF mutated colon cancer, regardless of the location of the primary lesion." (PMID 31203527, 2020). "In a pooled analysis of PETACC-8 and N0147, and a post hoc analysis of the PETACC-8, both included resected stage III colon cancer patients receiving adjuvant FOLFOX, BRAF or KRAS mutations are independently associated with the decreased DFS in patients with pMMR, but not dMMR tumors." (PMID 33344234, 2020). "We found that colon cancer tissues that had BRAF but not KRAS mutations demonstrated significantly lower concentrations of total ERK, AKT, cyclin d and activated ERK and AKT as compared to Wt." (PMID 33208845, 2020). "As BRAF is downstream of RAS in the MAPK/ERK signaling pathway, mutated BRAF is assumed to have the same resistance to the anti-EGFR agent as to the RAS-mutated colon tumor." (PMID 33254149, 2020). "Among the colon cancer cell lines, six (SW403, SW116, SW480, SW1463, MICOL29 and SW620) were characterized by a mutation in exon 2 of the KRAS gene and two (CO115 and HT-29) by the V600E mutation in the BRAF gene." (PMID 33233823, 2020). "However, several clinical trials testing BRAF inhibitors as single agents in BRAF-mutant colon cancer patients saw response in less than 5%, mostly of short duration." (PMID 32325878, 2020). "It is already well-established in the literature that tumors with extended RAS mutations, including NRAS and non-exon 2 KRAS mutations, BRAF mutations and right-sided colon tumors do not benefit from EGFR inhibition." (PMID 32384640, 2020). "The role of copper in the modulation of BRAF signaling is particularly relevant in colon cancer." (PMID 31083627, 2019). "Nevertheless, the finding is consistent with low levels of Axin2 and other Wnt target genes as well as the lack of APC mutation in MSI-H colon cancer cells with BRAF-V600E mutation." (PMID 31811196, 2019). "Furthermore, in colon cancer, RNF43-G659Vfs*41 mutation is most frequently associated with BRAF-V600E mutation and low Wnt/β-catenin signaling." (PMID 31811196, 2019). "Accordingly, it promotes p27 accumulation in the BRAF-mutant colon cancer cell line HT-29." (PMID 30992425, 2019). "Moreover, tetrathiomolybdate treatment was also effective in reducing the clonogenic potential of colon cancer BRAFV600E cells resistant to BRAF pharmacological inhibition." (PMID 31083627, 2019). "However, a molecular sub-cluster of colon cancer cells is specifically sensitive to chemotherapy, BRAF inhibitors and PI3K-mTOR inhibitors treatment suggesting those drugs share some similar inner mechanisms to determine their sensitivity." (PMID 31596728, 2019). "Overall, the results of these experiments demonstrates that IHC using the anti-BRAF V600E (VE1) antibody with the VENTANA OptiView DAB detection system and BenchMark ULTRA platform is a highly specific and sensitive method for the detection of BRAF V600E in colon cancer." (PMID 29127628, 2019).
colon carcinoma (continued). "The primary goal of this study was to compare the performance of the anti-BRAF V600E (VE1) antibody to detect BRAF V600E mutation by IHC in colon cancer cases with/without KRAS mutation." (PMID 29127628, 2019). "However, BRAF paradoxically inhibits stem cell renewal; also in BRAF-driven mouse model of colon cancer, tumor formation is suppressed." (PMID 31888644, 2019). "To gain further insights into the in vitro effect of copper chelation treatment on colon cancer cells with a different status in BRAF, we performed a scratch assay to evaluate the effect of pharmacological copper chelation on disrupted monolayers of HCT-116 and HT-29 cell lines." (PMID 31083627, 2019). "Based on a cohort of 48 stage I-II colon cancer patients, we set out to characterize consistent expression differences in sRNAs between cancer and normal tissue, and between colon cancer subtypes characterized by MSI status, BRAF and KRAS mutations, and tumor location." (PMID 30786859, 2019). "Our data suggest that TM treatment might also be effective on colon cancer BRAFV600E cells which are resistant to BRAF pharmacological inhibition." (PMID 31083627, 2019). "The mutation status of KRAS (exons 2, codon 12/13), NRAS (exons 2/3/4, codon 12/13/59/61/117/146) and BRAF (exons 15, codon 600) were detected by amplification refractory mutation system polymerase chain reaction (ARMS-PCR) in 86 colon cancer, 140 rectal cancer and 34 gastric cancer tissues." (PMID 30416987, 2018). "The frequency of BRAF mutations was markedly higher in hypermutated (47%) than in non-hypermutated (3%) colon cancers." (PMID 29652830, 2018). "More recently, Jass and coworkers proposed a classification of colon cancer based on five main criteria: CIN; MSI; CIMP, methylation status of 0–6-island methylguanine DNA Methyltransferase (MGMT); mutational status of KRAS and of BRAF." (PMID 29652830, 2018). "KRAS/NRAS/BRAF mutations were not significantly related to patients' age analyzed by Student's t-test or gender analyzed by Chi-square test in colon cancer." (PMID 30416987, 2018). "Characteristics of colon cancer patients and tumors according to BRAF and KRAS status." (PMID 29568398, 2018). "In this study, we investigated the mutation status of KRAS (exons 2, codon 12/13), NRAS (exons 2/3/4, codon 12/13/59/61/117/146) and BRAF (exons 15, codon 600) in 260 patients, including 86 cases of colon cancer, 140 cases of rectal cancer and 34 cases of gastric cancer." (PMID 30416987, 2018). "Interestingly, the BM1 colon cancer cells are more sensitive to the inhibition of BRAF, BCL2 and MEK compared to BM2; however, BM2 tumor cells are more sensitive to CDK1 inhibition, compared to BM1." (PMID 29652830, 2018). "However, due to the mutation and over-expression of EGFR/RAS/BRAF, the abnormal activation of EGFR/RAS pathway occurs frequently in colon cancers and is associated with a poor prognosis and drug resistance." (PMID 30185207, 2018). "Thus, inhibition of EGFR signaling by monoclonal antibodies (i.e., Cetuximab) or tyrosine kinase inhibitors (TKi; i.e., gefitinib or erlotinib) is synergistic with BRAF inhibition in colon carcinoma cells." (PMID 29033690, 2017). "Highly connected biomarkers (with degree centrality) were BRAF mutation (0.19) and methylation-related markers including CDKN2A (0.17), IGF2 (0.17), RUNX3 (0.17), CACNA1G (0.15), CRABP1 (0.15), and NEUROG1 (0.15) in the proximal colon cancer network." (PMID 28623901, 2017). "Among patients with non-MSI-high cancer, BRAF mutation status emerged as a distinct marker with higher connectivity in the network of proximal colon cancer, but not in distal colorectal cancer." (PMID 28623901, 2017).
colon carcinoma (continued). "A study with 364 stage II and III colon cancer patients reported a poor prognosis for patients with BRAF mutations in tumor independent of age, stage, grade, differentiation, MMR status, and location." (PMID 28378527, 2017). "Since in the initial experiments VLX60 was found most active against a cell line from colon cancer we included colon cancer models able to associate the activity to the KRAS and BRAF mutation status, established to have predictive and/or prognostic importance in this tumor type." (PMID 28415818, 2017). "In particular, Fariña-Sarasqueta and colleagues investigated the value of BRAF, microsatellite instability (MSI) and KRAS mutations on clinical outcome of 106 stage II colon carcinoma patients undergone surgery and 258 stage III patients treated with 5-fluorouracil chemotherapy." (PMID 27099668, 2016). "Moreover, it is not related to differences in the expression of the protein, in that CDC37 was expressed at comparable levels between colon cancer cell lines carrying wild-type BRAF and whose with mutant BRAF." (PMID 27391062, 2016). "In addition, we have shown that rebound activation of ERK and Akt caused respectively by the persistent expression of mutant BRAF and the activity of CDC37 is responsible for resistance of mutant BRAF colon cancer cells to AUY922." (PMID 27391062, 2016). "In addition, AUY922 triggered killing of mutant BRAF colon cancer cells with CDC37 knocked down in 3-dimensional cultures." (PMID 27391062, 2016). "An important finding of this study was that CDC37 knockdown not only blocked rebound activation of Akt in mutant BRAF colon cancer cells after treatment with AUY922, but also inhibited constitutive activation of Akt in mutant but not wild-type BRAF colon cancer cells." (PMID 27391062, 2016). "Indeed, knockdown of BRAFV600E conferred sensitivity of mutant BRAF colon cancer cells to AUY922-induced apoptosis." (PMID 27391062, 2016). "To examine whether remaining mutant BRAF (BRAFV600E) is involved in recovery of ERK activation in colon cancer cells after treatment with AUY922, we knocked down BRAFV600E using a siRNA specific for the mutant form of BRAF." (PMID 27391062, 2016). "This suggests that HSP90 inhibitors may be of particular importance in the treatment of colon cancers carrying mutant BRAF." (PMID 27391062, 2016). "Intriguingly, our results showed that knockdown of CDC37 caused a moderate decrease in the basal levels of ERK activation and reactivation of ERK after treatment with AUY922, suggesting that CDC37 is able to stabilize mutant BRAF independently of HSP90 in colon cancer cells." (PMID 27391062, 2016). "Moreover, mutant BRAF colon cancer cells were also relatively resistant to the other HSP90 inhibitor, XL888." (PMID 27391062, 2016). "In contrast, AUY922 markedly reduced Akt expression in wild-type BRAF colon cancer cells." (PMID 27391062, 2016). "In this study, we systematically interrogated the effect of inhibiting MEK and RAF on both MAPK signalling and AKT signalling in various colon cancer cell lines with and without mutations in BRAF and KRAS." (PMID 26799289, 2016). "However, it is intriguing that neither inhibition of HSP90 by AUY922 nor knockdown of CDC37 caused reduction in the expression of Akt that is a client of HSP90 in mutant BRAF colon cancer cells." (PMID 27391062, 2016). "Since CDC37 interacts with protein kinases and can stabilize and activate clients in concert with HSP90 or independently of HSP90, we investigated whether CDC37 is involved in reactivation of Akt in mutant BRAF colon cancer cells treated with AUY922." (PMID 27391062, 2016). "Therefore, the transient inhibitory effect of AUY922 on Akt activation in mutant BRAF colon cancer cells is primarily due to blockade of its upstream signals." (PMID 27391062, 2016). "However, while inhibition of ERK and Akt activation persisted in wild-type BRAF colon cancer cells, it was rapidly reversed in colon cancer cells carrying mutant BRAF." (PMID 27391062, 2016).
colon carcinoma (continued). "However, why HSP90 inhibition cannot efficiently degrade mutant BRAF in colon cancer cells remains to be clarified." (PMID 27391062, 2016). "Finally, we show that targeting ErbB-3 receptors in vivo, with a specific monoclonal antibody, significantly delays tumor growth of BRAF-V600E mutant colon cancer xenografts." (PMID 26160848, 2015). "Recently studies from the large case-control study suggested that smoking is related to CIMP (CpG Island Methylator Phenotype) and BRAF mutations in colon cancer, rather than with microsatellite-unstable cancer." (PMID 26530529, 2015). "The Raman results show that colon cancer cells experience a large spectral response to erlotinib, but colon cancer cells expressing oncogenic BRAF or KRAS mutations experience small or no relevant effects, respectively." (PMID 26168967, 2015). "In conclusion, our findings suggest that targeting ErbB-3 receptors could represent an effective therapeutic approach in BRAF-V600E mutant colon cancer." (PMID 26160848, 2015). "Therefore, there is a high degree of expectation in combination therapy of BRAF inhibitor and anti-EGFR antigen, etc. for BRAF mutation-positive colon cancer, and the outcome of future clinical trials is eagerly expected." (PMID 25936694, 2015). "This study aims to characterize colon cancer with regard to KRAS, BRAF, and PIK3CA mutations, microsatellite instability (MSI), and average DNA copy number, in connection with tumour dissemination and recurrence in patients with colon cancer." (PMID 25884297, 2015). "Traditionally, colon cancers developed in the proximal bowel often created an environment in which CIMP (CpG Island Methylator Phenotype) is more likely to arise, and this synergizes with BRAF mutation to allow progression of serrated polyps." (PMID 26042813, 2015). "Among GNAS mutant colon cancers, we identified mutations in the KRAS and BRAF oncogenes in nine of the ten (90%) cases, a fraction that is significantly higher than the overall frequency of KRAS and BRAF mutations in the tumor cohort (P<0.0305, Fisher's exact test)." (PMID 24498230, 2014). "BRAF V600E was associated with advanced TNM (P < 0.001), more distant metastases (P = 0.025), and worse overall survival (OS, P < 0.001; multivariate HR = 4.2, P = 0.004) in colon cancer patients." (PMID 25367198, 2014). "All BRAF and 80.8% PIK3CA mutations were from colon cancer patients." (PMID 25367198, 2014). "KRAS, BRAF and PIK3CA mutations are commonly found in colon cancers." (PMID 23617638, 2013). "Interestingly, although all colon cancer-, CIMP-, and BRAF mutation-specific differentially methylated regions are underrepresented for H3K4me3, this depletion is most evident for BRAF mutation-specific regions." (PMID 23324568, 2013). "Interestingly, several molecular markers (BRAF and PI3KCA, to cite some) have been found to be predictors of colon cancer risk and mortality in relation to aspirin and anti-inflammatory drugs consumption." (PMID 23965959, 2013). "For example, colon cancers with BRAF V600E mutations do not respond to vemurafenib due to feedback activation of EGFR." (PMID 23717811, 2013). "Further unraveling of the CIMP, BRAF, and MSI findings will enable us to target selected patients, identify their recurrence risk, and make decisions about their treatment options across all stages of colon cancer." (PMID 22792460, 2012). "We therefore assessed whether the influence of folate on colon cancer risk differed according to CIMP and BRAF status." (PMID 21738611, 2011). "Conferred resistance to the therapeutic combination by wild-type BRAF was also confirmed in two independent and genetically similar colon cancer cell lines, DLD-1 and HCT116, indicating only wild-type BRAF as the exclusionary factor for colon cancer treatment with PLX4720." (PMID 21738740, 2011). "B vitamins, methionine or alcohol intake did not affect colon cancer risk differentially by BRAF status." (PMID 21738611, 2011).
colon carcinoma (continued). "Patients with a BRAF mutation in a microsatellite-stable colon cancer have significantly poorer survival than those without the mutation, but the BRAF status does not affect survival of patients with microsatellite-unstable tumors." (PMID 21403829, 2011). "A prior case-control study of 1,154 colon tumors assessed the influence of one-carbon nutrient intake on CIMP as well as BRAF status in these tumors and found them not to be associated with either CIMP-high or BRAF mutation." (PMID 21738611, 2011). "Moreover, while the high frequency of KRAS, BRAF and PIK3CA mutations in colon cancer is well documented, other potentially important mutations have not been profiled with a large number of clinical samples." (PMID 20233444, 2010). "Dietary factors such as folate, vitamins, and methionine may be associated with colon cancer because of involvement in DNA methylation and hence on the CpG island, MSI and BRAF." (PMID 18718023, 2008). "Notably, 75% of BRAF-mutated tumors were located in the colon, reinforcing prior studies that associate the V600E mutation with colon tumors rather than rectal ones." (PMID 40949797, 2025). "Colon cancers exemplify such features wherein there is an increased likelihood of exhibiting the CpG-island methylator phenotype high (CIMP-high or CIMP-H), microsatellite instability high (MSI-high) and having BRAF mutations to dominate in the cancers occurring in the proximal colon." (PMID 38360902, 2024). "Moreover, the introduction of more refined imaging assessments and the use of molecular biology tests to identify specific biomarkers, such as MSI/MSS, Ras mutations, BRAF mutations, and HER2 amplification, have become crucial in determining appropriate management strategies for colon cancer." (PMID 38791928, 2024). "However, the identified SNVs are more promising than other biomarkers because, unlike SNVs in KRAS and BRAF, they target the entire colon cancer population, including rectal cancer, and are not rare like BRAF, nor are they expensive like circulating tumor DNA." (PMID 37784019, 2023). "Furthermore, Tgfβ signaling has also been found to be critical in suppression of BRAF-driven oncogenesis in right-sided colon cancers, suggesting that Smad4/Tgfβ plays a significant role in serrated colon cancer progression, yet there are still substantial gaps in the current knowledge." (PMID 38136364, 2023). "Significant heterogeneity in survival outcome characterizes colonic cancer patients with dysregulated BRAF expression due to the complex, and still not entirely fully elucidated, interactions between the clinical, genetic, and epigenetic landscape of BRAF expression." (PMID 36673047, 2023). "Additionally, tumor molecular markers, such as the microsatellite status, the CpG island methylator phenotype (CIMP) status, driver gene mutations, such as KRAS and BRAF, and tumor immune microenvironment, have been linked to different recurrence risks of stage III colon cancer." (PMID 36593480, 2023). "Second, neither BRAF mutation test nor MSI mutation test could be performed to identify effective treatment regimens for colon cancer." (PMID 37872388, 2023). "Moreover, MEIS1 inhibition is observed in BRAF-mutant colon tumors." (PMID 35743243, 2022). "Colon cancer was a highly heterogeneous disease, resulting from a series of distinct genetic and epigenetic changes, and a subset of molecular alterations was considered to drive the cellular and clinical behavior of cancer, including MSI, CIMP, CIN, BRAF, and KRAS mutations." (PMID 36276973, 2022). "Interestingly however, CTLA-4 blockade synergizes with BRAF inhibition in BRAF-wildtype colon carcinoma and fibrosarcoma mouse models; an effect attributed to the expansion of antigen specific T cells resulting from BRAFi-induced paradoxical activation of MAPK/ERK." (PMID 34025662, 2021).